PPRC1 (PPARG related coactivator 1)
Description:
Acts as a coactivator during transcriptional activation of nuclear genes related to mitochondrial biogenesis and cell growth. Involved in the transcription coactivation of CREB and NRF1 target genes.
Synonyms: PRC; KIAA0595; MGC74642
Tractability: PROTAC: ubiquitination databases record sites on it.
Gene: Protein-coding gene on chromosome 10 (102,132,994 to 102,150,333, forward strand). Ensembl gene ENSG00000148840.
Subcellular location: Nucleus
Subcellular location (Human Protein Atlas): Nucleoplasm
Pathways (Reactome):
Organelle biogenesis and maintenance: Transcriptional activation of mitochondrial biogenesis
Gene Ontology:
Molecular function: RNA binding; transcription coactivator activity; nucleic acid binding; transcription coregulator activity
Biological process: energy homeostasis; positive regulation of transcription by RNA polymerase II
Cellular component: nucleoplasm; nucleus
Genetic constraint (gnomAD): Loss-of-function variants: 23 observed, 131.22 expected, observed/expected ratio (o/e) 0.18, 90% interval 0.12 to 0.25. The upper end of that interval is the gene's LOEUF score, 0.25, which puts it in group 1 of 6, group 1 being the genes least tolerant of losing a copy. Missense variants: 2,006 observed, 2,164.7 expected, observed/expected ratio (o/e) 0.93, 90% interval 0.89 to 0.96. Synonymous variants: 871 observed, 866.06 expected, observed/expected ratio (o/e) 1.01, 90% interval 0.95 to 1.06.
Homologues: Orthologues: chimpanzee PPRC1 (99% identical), macaque PPRC1 (94% identical), dog PPRC1 (84% identical), pig PPRC1 (84% identical), rabbit PPRC1 (84% identical), guinea pig PPRC1 (78% identical), mouse Pprc1 (76% identical), rat Pprc1 (75% identical), tropical clawed frog pprc1 (34% identical), zebrafish pprc1 (24% identical), zebrafish si:dkey-93h22.8 (17% identical), Drosophila melanogaster srl (11% identical). Paralogues in human: PPARGC1B (13% identical), PPARGC1A (12% identical).
Diseases named in the same sentence as PPRC1 in open-access papers:
PPRC1 is named in the same sentence as 62 diseases in open-access papers, as found by Europe PMC text mining. Sharing a sentence is not in itself a finding about the gene and the disease. The quoted sentences say what the papers report.
Sepsis (4 papers, 2010 to 2023). Sepsis is defined as life-threatening organ dysfunction caused by a dysregulated host response to infection. "GO analysis of the DE RBPs in sepsis identified terms that were mostly enriched in the immune/inflammatory response; we identified significant differences in 8 down-regulated RBPs in sepsis, including DDX24, CBFA2T2, NOP, ILF3, DNMT1, FTO, PPRC1, NOLC1." (PMID 37749550, 2023). "Thus, the expression levels of the eight RBPs (DDX24, CBFA2T2, NOP14, ILF3, DNMT1, FTO, PPRC1, and NOLC1) were altered in the patients with sepsis might potentially be useful as novel biomarkers as well as targets to facilitate the diagnosis and management of sepsis." (PMID 37749550, 2023).
glioblastoma (3 papers, 2022 to 2025). The most malignant astrocytic tumor (WHO grade IV). "Recent literature reports have also shown that PPRC1 not only participates in regulating glioblastoma but also helps in diagnosing and understanding the pathogenesis of polymorphic low-grade neurons in young people." (PMID 37109742, 2023). "Transcriptomic dataset analyses predicted PPRC1 (Peroxisome Proliferator-Activated Receptor Gamma Coactivator-Related Protein 1) to be engaged in the regulation of actin polymerization under type V collagen overexpression, favoring cell mobility and metastatic process in glioblastoma." (PMID 40038783, 2025). "PPARG related coactivator 1 (PPRC1), a transcription factor and regulator of mitochondrial biogenesis, may become a new therapeutic target for glioblastoma." (PMID 36139663, 2022).
hepatocellular carcinoma (2 papers, 2020 to 2023). A malignant tumor that arises from hepatocytes. "The results of the present study revealed that PPRC1 may be a potentially critical biomarker suggestive of prognosis in ovarian and hepatocellular carcinoma." (PMID 37109742, 2023). "In addition, PPRC1 expression was found to be significantly correlated with immune cell infiltration, immune checkpoints, and the tumor-stemness index in both ovarian and hepatocellular carcinoma." (PMID 37109742, 2023).
liver cancer (2 papers, 2023 to 2025). An epithelial or non-epithelial malignant neoplasm that arises from the liver. "We have shown that the expression of PPRC1 is significantly higher in a substantial number of renal cancer, colon adenocarcinoma, lung adenocarcinoma, blood, breast, and liver cancer cases." (PMID 39996733, 2025). "We used HPA database to observe the differences in PPRC1 expression between normal tissues and ovarian cancer and liver cancer tissues." (PMID 37109742, 2023). "IHC results showed that the protein expression of PPRC1 was upregulated in ovarian cancer and liver cancer tissues compared to normal tissues." (PMID 37109742, 2023). "Through the HPA database we found differences in PPRC1 expression between normal tissues and ovarian cancer and liver cancer tissues." (PMID 37109742, 2023). "IHC results showed that the protein expression of PPRC1 in ovarian cancer and liver cancer tissues were upregulated compared to normal tissues." (PMID 37109742, 2023). "We have found that high PPRC1 expression significantly correlates with short overall survival (OS) in renal cancer (p < 0.0001; 877 patients), colon adenocarcinoma (p < 0.0092; 438 patients), lung adenocarcinoma (p < 0.033; 500 patients), and liver cancer (p < 0.0043; 365 patients)." (PMID 39996733, 2025).
ovarian carcinoma (2 papers, 2021 to 2023). A malignant neoplasm originating from the surface ovarian epithelium. "IHC results showed that PPRC1 protein expression levels were upregulated in ovarian cancer and cancer tissues compared to normal tissues." (PMID 37109742, 2023). "Secondly, combined with clinical-information data, we speculated that the expression of PPRC1 is negatively correlated with survival outcomes in ovarian cancer (OV) and liver hepatocellular carcinoma (LIHC) in terms of OS, DSS, and PFI." (PMID 37109742, 2023). "Therefore, we compared the differences in PPRC1 expression among normal tissue, ovarian cancer, and cancer using the HPA database." (PMID 37109742, 2023).
thyroid tumor (2 papers, 2018 to 2020). A benign or malignant neoplasm affecting the thyroid gland. "Interestingly, PPRC1 is commonly found to be overexpressed in thyroid tumor, concomitant with increased activity of cytochrome oxidase and expression of some subunits of the respiratory chain." (PMID 32639509, 2020).
Esophageal carcinoma (1 paper, 2023). A primary or metastatic malignant neoplasm involving the esophagus. "As for DSS, tumor patients with lower PPRC1 expression were found to have better survival outcomes in ACC, KIRP and LIHC, while higher PPRC1 was correlated with better DSS in Esophageal carcinoma(ESCA)patients." (PMID 37109742, 2023).
lymphoma (1 paper, 2025). A malignant (clonal) proliferation of B- lymphocytes or T- lymphocytes which involves the lymph nodes, bone marrow and/or extranodal sites. "However, unlike the transcriptome data, PPRC1 mutations, including gene amplification, are very low in breast, lymphoma, uterus, pancreas, and liver cases." (PMID 39996733, 2025).
pancreatic adenocarcinoma (1 paper, 2021). "Japonicone A affects PPRC1 expression that, in turn, affects the survival in patients with pancreatic adenocarcinoma." (PMID 34439361, 2021). "Six compounds are similar to Japonicone A which induces the down-regulation of PPRC1, which enhances the survival in pancreatic adenocarcinoma." (PMID 34439361, 2021). "The survival analysis in pancreatic adenocarcinoma demonstrates a high survival probability of individuals with medium/low expression level of PPRC1 than in individuals with high expression levels." (PMID 34439361, 2021). "Indole-3-carbinol affects the expression of 5 different genes (CD47, CENPB, ERGIC1, PPRC1, SLC44A1) that, in turn, affect the survival in patients with uterine corpus endometrial carcinoma (CD47), brain lower-grade glioma (CENPB, ERGIC1) and pancreatic adenocarcinoma (PPRC1, SLC44A1), respectively." (PMID 34439361, 2021).
cancer (21 papers, 2009 to 2025). A tumor composed of atypical neoplastic, often pleomorphic cells that invade other tissues. "PPRC1 mutations also correlated significantly with poor OS (p < 0.0001) when tested in a total of 23,456 cancer patients." (PMID 39996733, 2025). "In addition, PPRC1 gene mutations significantly correlate with short OS and/or disease-free survival in several cancers." (PMID 39996733, 2025). "Therefore, future research should focus more on using different experimental methods to verify the diagnostic and prognostic potential of PPRC1 in many cancers." (PMID 37109742, 2023). "Using large-scale cancer transcriptome, genomics, and clinical outcome datasets, we have shown that PPRC1 plays important roles in tumor progression." (PMID 39996733, 2025). "We have also shown that PPRC1 expression is higher in cancer cells from blood, breast, and other types of cancer relative to normal cells, and high PPRC1 levels correlate significantly with short overall survival (OS)." (PMID 39996733, 2025). "Since primary tumor cells and cancer cell lines express high levels of PPRC1, we sought to investigate the possible correlation between the expression level of the gene and clinical outcomes in cancer patients." (PMID 39996733, 2025). "Our extensive analysis of 1330 cancer and normal cases has shown that the PPRC1 expression was higher compared to normal tissues." (PMID 39996733, 2025). "Since immune cells in the tumor microenvironment are an important factor in targeting immunotherapy, we focused on exploring the correlation between PPRC1 expression and immune cells in pan-cancer." (PMID 37109742, 2023). "To further analyze the prognostic value of PPRC1 for survival in pan-cancer, we first analyzed the correlation between PPRC1 expression and different survival outcomes in various cancers, such as OS, DSS, and PFI." (PMID 37109742, 2023). "Taken together, it can be seen that PPRC1 can provide some guidance for tumor immunotherapy and promote personalized treatment of pan-cancer." (PMID 37109742, 2023). "We analyzed the role of PPRC1 in the prognosis of pan-cancer using Kaplan–Meier plotter and univariate Cox regression statistical methods." (PMID 37109742, 2023). "To confirm that the sequence of PPRC1 in different cancers was complete, we explored the relationship between PPRC1 expression and mutation status through the TIMER database." (PMID 37109742, 2023). "Importantly, in a very large cohort of 23,456 cancer patients, PPRC1 alterations were significantly correlated with short OS (p < 0.0001)." (PMID 39996733, 2025). "We have found PPRC1 to be highly expressed in most cancer cell lines." (PMID 39996733, 2025). "Next, we investigated the expression level of PPRC1 in cancer versus normal cells." (PMID 39996733, 2025). "Thereby, PPRC1 could be considered a promising therapeutic target not only for AML patients but also for other types of cancer." (PMID 39996733, 2025). "In fact, mutations at proline positions 938, 940, and 941 were found in eleven different cancer types, which suggests that disrupting these amino acid residues might activate the tumorigenesis function of PPRC1." (PMID 39996733, 2025). "In addition to this, further validation of our preliminary screening results at the molecular and clinical levels is needed to clarify the importance of PPRC1 in pan-cancer." (PMID 37109742, 2023). "Next, in order to clarify whether PPRC1 is differentially expressed in tumors, we analyzed the expression of PPRC1 in cancer and normal tissues from the TCGA database." (PMID 37109742, 2023). "In the future, research on PPRC1 expression and tumor immune microenvironment may help to provide clear answers and provide immune-based anti-cancer strategies." (PMID 37109742, 2023). "The gene PPRC1 is down-regulated under Al-10-49 apoptotic treatment, Indole-3-Carbinol and Japonicone A nutrigenomics treatments, while it is up-regulated in 3 different cancer types." (PMID 34439361, 2021).
cancer (continued). "PPRC1 is an activator of mitochondrial biogenesis, a process regulated by mTOR, highlighting the use of mTOR inhibitors in cancers with aberrant mitochondrial activity." (PMID 30803482, 2019). "Interestingly, three mutations at proline present in positions 938, 940, and 941 were identified in eleven types of cancer, which suggests that proline at these positions could be critical for the function of the PPRC1 protein." (PMID 39996733, 2025). "Similarly, a comparison of PPRC1 expression levels in cancer versus normal cells in different cancer types showed that PPRC1 expression was significantly higher (p < 0.001) in primary cells from the various cancer types tested." (PMID 39996733, 2025). "The PFI results showed that high expression of PPRC1 was significantly correlated with six cancer types, with a positive correlation with GBM and a negative correlation with ACC, BLCA, KIRP, LIHC, and UVM." (PMID 37109742, 2023). "However, the link between PPRC1 and tumor progression and/or clinical outcome of cancer patients still remains not well defined." (PMID 39996733, 2025).
tumor (20 papers, 2013 to 2025). "Secondly, we obtained the protein expression of PPRC1 in different tumor cell lines through the CCLE database, and there were differences." (PMID 37109742, 2023). "Our results showed that the proportion of tumor immune cells (B cells, CD4+ T cells, CD8+ T cells, neutrophils, macrophages, and dendritic cells) was significantly correlated with PPRC1 expression in 33 out of 38 tumor types." (PMID 37109742, 2023). "Therefore, it is clear that only by fully regulating the expression level of PPRC1 can we indirectly regulate the anti-tumor immune response, thereby exerting an immunotherapeutic effect." (PMID 37109742, 2023). "In summary, we hypothesized that, based on the results of comprehensive analysis of multiple databases, PPRC1 expression was significantly correlated with tumor immune cells, immune-checkpoint genes, and tumor stemness." (PMID 37109742, 2023). "Finally, the heterogeneity of PPRC1 expression in different tumor types suggests that it is oncogenic, a result consistent with some previous reports in the literature." (PMID 37109742, 2023). "In addition, the correlation between PPRC1 expression and tumor immune cell infiltration, immune checkpoints, and the tumor-stemness index was analyzed using TCGA and TIMER databases." (PMID 37109742, 2023). "In the present study, PPRC1 expression was found to be negatively correlated with DNAss in most tumors, especially in OV, GBM, and LIHC, suggesting that low PPRC1 expression corresponds to a strong tumor cell stem, which also suggests easy promotion of tumor proliferation and metastasis." (PMID 37109742, 2023). "In addition, there is a significant positive correlation between the expression of PPRC1 and tumor immunity in OV and LIHC." (PMID 37109742, 2023). "In addition, the results suggest that the expression of PPRC1 may regulate tumor immunity in OV and LIHC." (PMID 37109742, 2023). "On the other hand, our analysis shows that PPRC1 expression is independent of age, gender, and tumor stages." (PMID 39996733, 2025). "SL exposure also induced changes in the expression of genes involved in metabolic functions in tumor and stem cells (ALDH1B1, ABCB1, SLC3A2, SLC44A2, SLC31A2, SLC7A11, CYP24A1, PTGS2/COX2, PPRC1), cytokines (CCL3L3, GDF15) and growth and differentiation factors (PGF, TGFBR11 and FOXD1)." (PMID 24742967, 2014). "However, correlations of PPRC1 genetic alterations with clinicopathological characteristics, such as tumor stage, sex, and age, have shown no substantial difference." (PMID 39996733, 2025). "Although we used various bioinformatics databases to speculate on the close relationship between PPRC1 and tumor immune cells, there was no way to carry out more experiments to verify this hypothesis." (PMID 37109742, 2023). "In addition, in the tumor microenvironment, we found that PPRC1 expression in LIHC and OV had the same trend as some immune-cell molecular markers such as CD200, CD200R1, and LAIR1, although, in SKCM we found that PPRC1 expression had the opposite trend to that of some immune cell molecular markers." (PMID 37109742, 2023).
PPRC1 also shares sentences with these, for which no sentence is quoted: prostate carcinoma (6 papers); breast cancer (5); lung carcinoma (4); infection (3); melanoma (3); stomach cancer (3); benign prostate hyperplasia (2); bladder cancer (2); depression (2); Ewing sarcoma (2); renal carcinoma (2); Stroke (2); brain cancer (1); calculus (1); cognitive decline (1); colon adenocarcinoma (1); colon cancer (1); colorectal cancer (1); endothelial dysfunction (1); follicular thyroid carcinoma (1); hereditary cancer (1); hyperlipidemia (1); ischemia (1); kidney damage (1); kidney disease (1); lung adenocarcinoma (1); metabolic disease (1); metastatic disease (1); multiple myeloma (1); multiple sclerosis (1).
A further 21 diseases each share a sentence with PPRC1 in 1 paper.